IL2 (interleukin 2)
Diseases named in the same sentence as IL2 in open-access papers (continued):
Sharing a sentence is not in itself a finding about the gene and the disease.
cancer (continued). "However, the peptide‐based vaccines combined with low‐dose IL‐2 (interleukin‐2) may exert negative effects on anti‐cancer therapies due IL‐2 may increase Tregs." (PMID 33754407, 2021). "The most studied drug was IL-2, which was used as a cancer immunotherapy, and the incidence of CLS was 34.7% by overall estimation, suggesting that it may be a common adverse effect, and that the phenomenon of CLS has been underestimated in cancer patients in the past." (PMID 30691103, 2019). "However, the risk in these settings may be no greater than that of many widely used cancer cytotoxics (e.g., doxorubicin), antiangiogenic agents (e.g., bevacizumab), and biologics (e.g., IL-2), which are known to exacerbate the same vascular conditions." (PMID 27458571, 2016). "Interestingly, it was demonstrated that ADCC- and IL-2-activated NK cells were less susceptible to immunosuppression by chemotherapy or other immunosuppressive drugs, especially mycophenolate mofetil (MMF), than non-stimulated NK cells in cancer patients." (PMID 26579120, 2015). "Agents like interleukin-2 (IL-2) and alpha-interferon(IFN-α) have shown limited effectiveness and extensive toxicity,and many cancer vaccines have not achieved the expected results inclinical trials." (PMID 38990186, 2024). "Significant levels of IL-2, IFN-ɣ and TNF-α were detected in supernatants of CD4+ nfP2X7-M-CAR-T cells co-cultured with MDA-MB-231 and U87 cancer cell lines, but not when co-cultured with either SK-ND-Z or K562 cells." (PMID 37684239, 2023). "Unlike HMGB1, IFNA1, IFNA2, IL-2, KIR2DL3, IL-13 and NCAPG2 demonstrated an intuitive correlation in only a few cancer types." (PMID 36776838, 2023). "S1-specific IgG levels correlated with IL-2 and IFN-γ responses in controls and IBD patients, but not in cancer patients." (PMID 35634285, 2022). "A persistence of CCGs such as TNF-α, IL-2, and MCP-3 was also observed for exposed cancer patients but not for the healthy control group." (PMID 34830872, 2021). "For example, the Interleukin-2 (IL-2)/Signal Transducer and Activator of Transcription 5 (STAT5) axis is critical for Treg cell differentiation and function, but its role in cancer has not been formally evaluated yet." (PMID 33143070, 2020). "When activated with IL-2, NK92 cells were found to have no/low cytotoxicity against NK sensitive cancer stem cells; however, they retained the ability to secrete high levels of regulatory cytokines IL-6 and IL-10 with no or slight secretion of IFN-γ and TNF-α." (PMID 26247631, 2015). "T cells from cryopreserved leukapheresis products of three patients with gastrointestinal (2 colorectal and 1 pancreatic) cancers were activated by anti-CD3 mAb with or without ipilimumab and expanded for 14 days with IL-2." (PMID 25008236, 2014). "Notably, some inflammation-related pathways were up-regulated exclusively by both cancer plasmid models without TAA but not TAA alone, including IL2/STAT5 signaling, IL6/JAK/STAT3 signaling, and interferon alpha response." (PMID 39254423, 2024). "In the absence of monocytes, NK cells from cancer patients exhibited suppressed IFN-γ secretion when treated with IL-2 alone, or IL-2 + anti-CD16 mAbs, but increased IFN-γ secretion in cancer patients’ NK cells were seen when treated with IL-2 + sAJ2." (PMID 35203349, 2022). "The CD4+ T cells obtained from two different healthy donors were polyclonally stimulated with anti-CD3/CD28/CD2 moAb-coated beads and with IL-2 for 12 days, then subsequently polyclonally restimulated for next 3 days without IL-2 in the presence or without MDA-MB-231 cancer cells." (PMID 34439305, 2021). "However, in the studies conducted with IL-2 in chronic HIV-infection, with more than 3,000 patients, no increased incidence of cancer was seen." (PMID 26186440, 2015). "However, unlike IL-2, IL-15 does not support regulatory T cell populations or promote activation induced cell death (AICD), both of which may inhibit anti-cancer immune responses." (PMID 26500048, 2015).
cancer (continued). "Thus, the upregulation of NKp30 expression, as shown here by the ectopic overexpression, may be an alternative and viable strategy to improve the outcomes of NK cell immunotherapy for patients with cancer, particularly AML, without potential risks of IL-2 infusion." (PMID 38698855, 2024).
infection (1,234 papers, 1999 to 2026). The state of being infected such as from the introduction of a foreign agent such as serum, vaccine, antigenic substance or organism. "Gene expression of pro-inflammatory cytokines IL-1β, IL-2, IL-4, and IL-6, as well as IFNγ was significantly upregulated in nasal turbinates in response to infection with all VOCs, with the Gamma variant inducing the highest inflammatory response." (PMID 40295859, 2025). "All human infection phenotype SNPs in linkage were associated with changes in patient IL-2 levels; in our previous study, we found that IL-2 levels were significantly higher in the ST93A subpopulation compared to ST93B." (PMID 39601574, 2025). "Separating individuals with TBI based on time since likely Mtb exposure revealed that more recent infection was associated with reduced IFNγ responses and a higher proportion of IL-2/TNF-secreting cells." (PMID 41159744, 2025). "Compared to untreated mice, DEM treatment of M.tb-infected mice caused a significant 35% increase in the levels of IL-2 at 8 weeks post-infection and treatment." (PMID 40001899, 2025). "A linear regression analysis was performed to evaluate the association between HAdV-36 infection and levels of IL-10, IL-2, IL-6, IL-8, and TNF-α." (PMID 40284995, 2025). "As such, we were able to provide empiric evidence that IFN-γ-secreting T cell responses are formed early during primary infection and associate with viral control whereas development of IL-2 responses occurs relatively later in infection." (PMID 40472803, 2025). "In contrast, more highly differentiated immune memory-associated IL-2-secreting T cells exhibited a delayed but sustained expansion, remaining elevated 28 days post-infection, which likely contributes to the formation of a durable pool of CD4+ memory T cells." (PMID 40472803, 2025). "Reduced systemic viral load linked to increased expression of IL-2 during infection with a highly virulent strain of Newcastle disease virus in chickens is also reported." (PMID 39066318, 2024). "In the large intestine, infection with the Alpha strain strongly correlated with IL-2, and Beta and Delta infections were highly associated with multiple inflammatory cytokines (IL-1β, IL-6, IL-8, IL-18, TGF-α and MIP-1α)." (PMID 38563680, 2024). "Because antigen presentation to T cells is rapid, we measured IL-2 at 4 h post-infection and 4 h post-overlay of T cells." (PMID 38975346, 2024). "Our findings demonstrate that MRTF/SRF-dependent cytoskeletal dynamics are essential for the homotypic CD8+ T-cell interactions that underlie IL-2 induced CD8+ T-cell proliferation during infection." (PMID 39261466, 2024). "Some studies suggest that IL-2 cytokine family rise during the infection and cause severe inflammatory response and cytokine storm." (PMID 37649897, 2023). "In particular, the signature based on IL-2, IP-10, and IL-9 detection was associated with TB status (infection/disease)." (PMID 38076244, 2023). "The levels of GM-CSF and IL-2 remained low in beta variant-infected mice over the course of infection." (PMID 36005818, 2022). "Global IFNAR deficiency leads to decreased expression of IFN gamma and IL-2 by CD8+ T cells during MHV68 infection." (PMID 35968944, 2022). "IL-2, IL-5, IL-17F, IFNγ and TNFα inductions were positively associated with the infection status in the N-peptides restimulated cells (308%, 65%, 39%, 304% and 40% increase when infected, respectively, FDR < 0.1)." (PMID 35313592, 2022). "Infection with A. actinomycetemcomitans as a single species caused a significant increase in IL-2, CXCL1, CCL-3/MIP1α, and G-CSF levels compared to sterile implants." (PMID 35203495, 2022). "In contrast, Ld-IL2 therapy was identified as a factor negatively associated with infection incidence (OR = 0.11, 95% CI 0.06 to 0.21, P-value < 0.001)." (PMID 34618873, 2021). "Despite the positive association between infection risk and disease activity and corticosteroid dose, we observed a 17.8% (7.3% in the IL-2 group v." (PMID 34618873, 2021).
infection (continued). "Supporting this tenet, reduced CD25 expression in aged Foxp3+ cells (X-axis, X-axis) and their likely inability to regulate IL-2 is likely associated with their dysfunction and immunopathology during infection in aged mice." (PMID 33240286, 2020). "OAd.TNFa-IL2 infection caused significantly higher IL-12p35 levels in both wt and KO cells compared to mock treated wt tumors." (PMID 32225009, 2020). "In support of this, greater numbers of dengue specific CD8s producing TNFα, IFNγ, and IL-2 prior to heterotypic infection was associated with an asymptomatic infection." (PMID 31816907, 2019). "By contrast, the relatively-more-potent immunosuppressant rATG can reduce the risk of acute rejection as compared with IL2-RA, but also induces higher rates of infection and other side effects." (PMID 30902050, 2019). "In our study, the use of WBA with IL-2 quantification also helped establish the risk factors that influence exposure to and infection by Leishmania." (PMID 31164191, 2019). "We demonstrate that adult Loa loa worms in subcutaneous tissues, circulating microfilariae (mf) and presence of filarial biomarkers in sera occur following experimental infections of lymphopenic mice deficient in interleukin (IL)-2/7 gamma-chain signaling." (PMID 30926803, 2019). "In contrast to IFN-ɣ and IL-2, mRNA expression of IL-12p35, a subunit of the Th1-associated cytokine IL-12, was significantly increased on SD 8 after infection." (PMID 29973271, 2018). "On the other hand, higher frequencies of Tcm cells producing IFN-γ/TNF-α/IL-2 early after infection were associated with vaccine-elicited protection and bacterial arrest by the host." (PMID 27799930, 2016). "In mammals, IL-2-dependent activation of effector cells has been proven important to control infection caused by viruses, such as HSV-1, cytomegalovirus, and lymphocytic choriomeningitis virus (in the persistent infection phase)." (PMID 26253150, 2015). "Infection caused by L. guyanensis accounted for 73% of the cases and patients with this parasite also showed higher concentrations of IL-2, IFN-γ, IL-4, and IL-17 when compared to infection by L. amazonensis." (PMID 25295285, 2014). "Diarrhea can complicate IL-2 administration due to fluid loss, electrolyte loss, local discomfort, inflammation, and even infection." (PMID 31546315, 2014). "The withdrawal of IL-2 not only inhibited de novo FIV infection, it also stopped cell growth and caused a drop in cell viability." (PMID 23201205, 2013). "As expected, the genes encoding IFNγ and IL2 cytokines, two biomarkers of infection, were significantly upregulated in the infected group." (PMID 22815916, 2012). "We recently showed that the development of protection against infection with P. falciparum in human volunteers is associated with the induction of IFNγ+IL-2+ double-positive (polyfunctional) EM T cells in response to PfRBC." (PMID 22144890, 2011). "We found that children 1–14 years old produced IP-10 and IL-2 in significant amounts after antigen-stimulation and we found a strong correlation between the biomarkers and risk of infection." (PMID 18682747, 2008). "Additionally, the increase in IL-2 becomes evident later in the mesenteric lymph nodes, at 35 d.p.i., highlighting that the immune response at the site of infection occurs more rapidly than in the associated lymphoid tissues." (PMID 39899646, 2025). "It has been demonstrated that the initial frequency of IL-2 secreting cross-reactive memory T cells is associated with protection of naïve individuals from infection in COVID-19 contacts, and SARS-CoV-2-reactive IFN-γ-secreting T cells have been associated with protection from reinfection." (PMID 36268016, 2022). "The Th1 profile produces cytokines such as interferon-gamma (IFN-γ), tumor necrosis factor (TNF), and interleukin 2 (IL-2), which are associated with the control of infection by macrophages, the production of nitric oxide (NO), and the consequent destruction of intracellular parasites." (PMID 35844611, 2022).
infection (continued). "Sex differences might be explained by the regulatory role of estrogens on cytokines, reducing IL-2 production and the proliferation of splenic T cells and resulting in higher susceptibility to infection." (PMID 35883327, 2022). "Taken together, it is justifiable to suppose that restoration of NK cell activity (e.g. through low-dose IL-2) could potentially help regain immune balance and minimize both systemic autoimmunity and the risk of infection in SLE patients." (PMID 35172900, 2022). "In summary, the investigation of Ld-IL2 therapy in patients and mouse models provided insights for the clinical application and further optimization of Ld-IL2 therapy for autoimmune patients, particularly for those with the risk of infections." (PMID 34618873, 2021). "During acute infection by this helminth, a strong Th1 immune response characterized by high levels of IL-2 and IFN-γ is induced and has been associated with host protection, but as the infection progresses, levels of both IL-2 and IFN-γ decrease as well as IL-12 produced by macrophages." (PMID 34684235, 2021). "Similarly, the multivariate analysis in matched groups showed that Ld-IL2 was a protective factor to reduce infection risk in SLE patients (OR = 0.13, 95% CI 0.07 to 0.23, P-value < 0.001)." (PMID 34618873, 2021). "Infection with pH1N1-alone also resulted in upregulation in “Signaling by Interleukins”, with 44 associated proteins from our kinome arrays, in addition to upregulation of IL-1, IL-2, and IL-6." (PMID 33202895, 2020). "Hence, the aim of this study was to investigate the effects of OAd.TNFa-IL2 infection on PRR-mediated danger- and pathogen-associated molecular pattern (DAMP and PAMP, respectively) signaling." (PMID 32225009, 2020). "Downregulation of IL-2 could be corroborating in the suppression of cell-mediated immunity and causing susceptibility to infection." (PMID 31978095, 2020). "In contrast, lower IL-8 and higher IL-2 were associated with peripheral infection in MG women." (PMID 29743113, 2018). "Additionally, the ability to produce cytokines IFNγ, TNFα, and IL-2 was unaffected in aPKC-deficient CD8+ T lymphocytes at 50 days post-infection." (PMID 26765121, 2016). "The loss of Th2 cell accumulation with Chit1 deficiency was responsible for attenuation of disease, because the use of IL-2 complexes to boost Th2 cell numbers and associated cytokines also hastened lethal disease in Chit1−/− mice compared with infection-matched, untreated Chit1−/− controls." (PMID 25764512, 2015). "In the i.n. model, infection by vΔ169 caused enhanced production of several cytokines (IL-2, IL-6 and TNF-α) and chemokines (CCL11, CXCL9 and CXCL10) within 1 day p.i. and subsequent greater recruitment of macrophages and CD4+ and CD8+ T cells and increased lung weight." (PMID 26334635, 2015). "However, it suggests similarity to the acute responses to the infection agents associated with a limited amount of available IL-2." (PMID 25145773, 2015). "Infections were a frequent cause of adverse events and even death in early trials of HD IL-2." (PMID 31546315, 2014). "Similarly, during acute infection with Toxoplasma gondii and Listeria monocytogenes a transient loss of Treg cells caused by IL-2 insufficiency was essential for initiation of Th1 responses and host protection against infection." (PMID 24456653, 2014). "Chickens vaccinated with profilin plus ISA 71 and infected with all 3 Eimeria parasites had greater levels of intestinal IEL gene transcripts encoding IFN-γ, IL-2, IL-10, and/or IL-17A at 3 days post-infection compared with infected birds vaccinated with profilin alone." (PMID 23593150, 2013). "We found that, whilst increasing in number, the IL-4gfp+CD4+ Th2 cells became conditioned towards a functionally hypo-responsive phenotype as infection progressed denoted by a progressive loss in their intrinsic ability to produce the cytokines IL-4, IL-5 and IL-2." (PMID 23516361, 2013).